SRC (SRC proto-oncogene, non-receptor tyrosine kinase)
Diseases named in the same sentence as SRC in open-access papers (continued):
Sharing a sentence is not in itself a finding about the gene and the disease.
Obesity (14 papers, 2010 to 2025). Accumulation of substantial excess body fat. "The SRC gene is involved in regulating adipocyte differentiation and energy expenditure, influencing obesity risk." (PMID 38827792, 2024). "SRC, a critical coactivator of ERα, downregulates lipolysis-related genes (e.g., ATGL and HSL) upon deficiency, leading to lipid accumulation and obesity." (PMID 41137228, 2025). "Various genes play a significant role in obesity and other cardiometabolic complications, either directly or indirectly, such as SRC." (PMID 38827792, 2024). "SRC (steroid receptor coactivator) enhances pro-inflammatory cytokine production of ATMs in diet-induced obesity including IL-17." (PMID 35885044, 2022). "According to the PPI network analysis of hispidulin anti-obesity targets, SRC (proto-oncogene tyrosine-protein kinase Src), EGFR (epidermal growth factor receptor), and AKT1 (AKT serine/threonine kinase 1) were the top three genes based on the degree." (PMID 34944408, 2021). "The intersection of the results from these two plugins revealed that PIK3R1, PIK3CB, SRC, PIK3CA and PIK3 CD are core targets for the combined treatment of obesity via Crataegus pinnatifida andgut microbiota." (PMID 41032481, 2025). "The common targets of obesity, T2DM, and AS are estrogen receptor 2 (ESR2), androgen receptor (AR), CYP19A1, NR3C1, SRC, and arachidonate 5-lipoxygenase (ALOX5)." (PMID 39575382, 2024). "Through a network pharmacology analysis, the anti-obesity effect of hispidulin was predicted to act on estrogen, prolactin, Rap1, and PI3K-Akt signaling pathways by targeting AKT1, SRC, EGFR, and GSK3B." (PMID 34944408, 2021). "Through network pharmacology analysis, we revealed that SMs of Crataegus pinnatifida and obesity-related gut microbiota could target obesity by interacting with PIK3R1, PIK3CB, SRC, PIK3CA and PIK3 CD." (PMID 41032481, 2025). "In the present study, network pharmacology results showed that Crataegus pinnatifida combined with the obesity-related gut microbiota may treat obesity by targeting PIK3R1, PIK3CB, SRC, PIK3CA, PIK3 CD." (PMID 41032481, 2025). "AKT1, SRC, EGFR, and GSK3B were identified as key anti-obesity target genes of hispidulin, and estrogen, prolactin, Rap1, and PI3K-Akt signaling pathways were predicted to be involved in the anti-obesity effects of hispidulin." (PMID 34944408, 2021). "In contrast, in obesity and insulin resistance, excess ROS have been shown to modify mitogen‐activated protein kinase (JNK, p38), SRC, and IKKβ signaling, either indirectly through oxidation of phosphatases and other endogenous inhibitors, or through direct oxidation of the kinase." (PMID 31464373, 2019). "The core targets between estrogen and obesity are proto-oncogene, non-receptor tyrosine kinase (SRC), estrogen receptor 1 (ESR1), prostaglandin-endoperoxide synthase 2 (PTGS2), nuclear receptor subfamily 3 group C member 1 (NR3C1) and cytochrome P450 family 19 subfamily A member 1 (CYP19A1)." (PMID 39575382, 2024).
osteopetrosis (14 papers, 2013 to 2022). Osteopetrosis, also known as marble bone disease, is a descriptive term that refers to a group of rare, heritable disorders of the skeleton characterized by increased bone density on radiographs. "As reported in previous work, the deletion of c-SRC in mice can alert the osteoclast with reduced bone resorption, leading to osteopetrosis." (PMID 36431913, 2022). "Global c-SRC knockout mice display osteopetrosis owing to defective osteoclast activity but the phenotype of these mice in NAFLD models has not yet been investigated." (PMID 34660604, 2021). "Although the numbers of osteoclasts increased compared with that in wild-type mice, Src−/− mice developed osteopetrosis, suggesting the vital role of SRC in osteoclast function rather than differentiation." (PMID 29515110, 2018). "The SRC gene has been shown to be involved in osteopetrosis due to non-functional osteoclasts." (PMID 31783652, 2019).
pulmonary fibrosis (13 papers, 2015 to 2025). Chronic progressive interstitial lung disorder characterized by the replacement of the lung tissue by connective tissue, leading to progressive dyspnea, respiratory failure, or right heart failure. "Another feature of our study is the focus on SRC inhibition in pulmonary fibrosis and especially as mediator of IPF-ABC profibrotic effects." (PMID 36163190, 2022). "Overall, these findings revealed that KX-01 can alleviate experimental pulmonary fibrosis via suppressing the p-SRC/p-STAT3 signaling pathways." (PMID 34349652, 2021). "Furthermore, we identified that SRC, which is known to regulate lung fibrosis through signaling pathways mediated by SRC/FAK, was upregulated with TGF-β1 treatment compared to that of TGF-β3." (PMID 34827680, 2021). "Intriguingly, a recent study described that quercetin in combination with the SRC/ABL protein kinase inhibitor dasatinib reverses bleomycin-induced pulmonary fibrosis in aged mice through the reduction of various senescence markers, thereby improving lung function." (PMID 32349726, 2020). "However, SRC is demonstrated to be active in renal and pulmonary fibrosis." (PMID 36297027, 2022). "Increasing evidence suggests that Src family kinases (SFKs), including SRC and HCK, which are strongly correlated with ADAM15, are involved in the pathogenesis of pulmonary fibrosis." (PMID 39824903, 2025). "In the present study, we found that KX-01 treatment was sufficient to reduce p-SRC and p-STAT3 levels and to thereby alleviate pulmonary fibrosis." (PMID 34349652, 2021). "protein–protein interaction protein interaction network analysis showed that PIK3CA, PIK3R1, MAPK1, SRC, AKT1, and so on may be the core targets of the compound Hongjingshen recipe in the treatment of pulmonary fibrosis." (PMID 36595795, 2022).
pancreatic ductal adenocarcinoma (12 papers, 2015 to 2024). An infiltrating adenocarcinoma that arises from the epithelial cells of the pancreas. "For example, ANXA2 Y24, a SRC-regulated site, has recently been reported to correlate with invasiveness and metastatic events in pancreatic ductal adenocarcinoma, underlining the established role of MET in driving invasive growth during tumorigenesis." (PMID 36494469, 2022). "Prior studies have revealed the potential dysregulation of SRC signaling in pancreatic ductal adenocarcinoma (PDAC) due to the alterations in CBL, where CBL acts as a pivotal molecule in modulating SRC and/or PI3K/AKT signaling." (PMID 39130630, 2024). "We recently found that the high expression of the mesenchymal FGFR2c variant in human pancreatic ductal adenocarcinoma (PDAC)-derived cells triggers the PKCε-mediated improvement of EMT and of MCL-1/SRC-dependent cell invasion." (PMID 38339360, 2024). "And the activated SRC-AKT signaling was reported to contribute to chemoresistance in pancreatic ductal adenocarcinoma cell lines." (PMID 37249822, 2023). "We have previously shown in pancreatic ductal adenocarcinoma (PDAC) cells that the SRC inhibitors PP2 and PP1 effectively inhibited TGF-β1-mediated cellular responses by blocking the kinase function of the TGF-β type I receptor ALK5 rather than SRC." (PMID 26588899, 2015). "A previous study in pancreatic ductal adenocarcinoma showed that ASPH could activate SRC signaling in cancer cells." (PMID 38817852, 2024). "The existing literature has emphasized that the amplification of the EMT and FAK/SRC/ERK axes may contribute to the metastasis of pancreatic ductal adenocarcinoma by upregulating KLK-10 expression." (PMID 37686036, 2023). "Previous studies revealed that ASPH could promote the EMT process of cancer cells via SRC signaling activation in pancreatic ductal adenocarcinoma." (PMID 36982561, 2023).
squamous cell carcinoma (12 papers, 2010 to 2024). A carcinoma arising from squamous epithelial cells. "Recently, it has been demonstrated that AMBRA1 controls the focal adhesion kinase 1 (FAK1)-mediated signaling pathway by interacting with FAK1 and SRC ﻿in mouse squamous cell carcinoma cells." (PMID 33953176, 2021). "High expression of PTPRA led to the dephosphorylation of SRC and thereby FAK mediated cell migration in epidermoid carcinoma cells." (PMID 36393868, 2022).
COVID-19 (11 papers, 2021 to 2024). A disease caused by infection with severe acute respiratory syndrome coronavirus 2. "In the lungs, COVID-19 causes lung dysfunction by regulating the expression of SRC, RHOA, CD40LG, CSF1, and TNFRSF1A." (PMID 34504502, 2021). "Several kinases, such as NTRK1 (10,495th → 29th), FYN (3902nd → 46th), ABL1 (7261st → 91st), and SRC (8965th → 56th), are being studied for repurposing several kinase inhibitors for COVID-19 treatment." (PMID 36291657, 2022). "Using lung sections from COVID-19 patients, we observed CD8+ T cells appearing in the KRT5+ lung area and p-SRC and nuclear YAP expression in KRT5+ cells." (PMID 39352385, 2024).
Insulin resistance (11 papers, 2017 to 2025). Increased resistance towards insulin, that is, diminished effectiveness of insulin in reducing blood glucose levels. "Mitochondrial damage interacts with insulin resistance and promotes apoptosis, and it targeted SRC ameliorated palmitate-induced insulin resistance." (PMID 36359184, 2022). "Similarly, we observed that SOS2 was another seeder gene that was linked with SRC, INSRR, EGFR, FGFR1, PGFRA and PGFRB gene signatures that were significantly associated with insulin resistance and type 2 diabetes." (PMID 28179884, 2017). "Notably, our analysis revealed crucial hub targets such as EGFR, SRC, ESR1, MAPK1, and CASP3, alongside implicated signaling pathways, including those related to insulin resistance, the FoxO signaling pathway, the PPAR signaling pathway, and the IL-17 signaling pathway." (PMID 38845779, 2024).
liver fibrosis (11 papers, 2015 to 2024). "Members of the SRC family kinases have been broadly investigated in cancer due to their pro-oncogenic characteristics, and results for SRC targeting have also been reported in the treatment of hepatic fibrosis." (PMID 37478207, 2023). "Previously, SRC inhibitors have been reported to induce autophagy in cancer cells and an increase in autophagy has an inhibitory effect on liver fibrosis." (PMID 32120837, 2020). "Total of 192 potential targets were obtained from 108 active ingredients after removing the redundancy, including MDM2, TNFBR1, MAPK14, and SRC, involved in inflammation, hepatic lipid metabolism, and the development of hepatic fibrosis." (PMID 31354851, 2019). "In this work, we show for the first time the changes exerted by liver fibrosis in the expression of activating and inactivating phosphorylation sites of c-SRC in both human and rat liver samples." (PMID 26696895, 2015). "RhoA expression was significantly elevated in human and experimental liver fibrosis, while c-SRC was inactivated." (PMID 26696895, 2015). "Considering core targets of the PPI network and a network of the common targets and pathways enriched, AKT1, MAPK1, EGFR, MTOR, and SRC may be the core potential targets of CL against hepatic fibrosis." (PMID 37478207, 2023). "Considering the main targets showed by PPI network, we speculate that AKT1, MAPK1, EGFR, MTOR, and SRC may be the core potential targets of CL against hepatic fibrosis, and molecular docking was further performed." (PMID 37478207, 2023). "Then, module analysis of the 113 key OGEs was performed using MCODE and the CytoNCA plugin to obtain 6 core genes (CXCL8, MAPK1, AKT1, SRC, VEGFA, and IL-6), which might play important roles in the effects of JQH against WD-associated liver fibrosis." (PMID 35707473, 2022). "Hence, we thought that RGGs presented anti-liver fibrosis activity by regulating the expression of SRC, PIK3R1, STAT3, AKT1 and other core targets." (PMID 35115923, 2021). "However, little is known about the role of c-SRC and the interplay with RhoA in liver fibrosis in general and in activated HSCs in particular." (PMID 26696895, 2015). "ECM components are responsible for increased matrix stiffness in liver fibrosis and may influence expression of c-SRC via growth factor or hyaluronan receptors (e.g., CD44) or focal adhesion complexes." (PMID 26696895, 2015). "Besides increased matrix stiffness, which is only one factor of liver fibrosis, the crosstalk of RhoA, and c-SRC may be triggered by other factors such as proinflammatory or profibrotic cytokines upon liver disease progression." (PMID 26696895, 2015). "A PPI network showed that as hub and core targets, SRC, PIK3R1, STAT3 and AKT1 were potential anti-liver fibrosis targets of RGGs." (PMID 35115923, 2021). "Non-receptor tyrosine kinase (SRC) can alleviate liver fibrosis by inhibiting hepatic stellate cell activation and reducing connective tissue growth factor." (PMID 37165407, 2023). "Both curcumin and demethoxycurcumin were strongly bound to MAPK1, EGFR, and SRC, which indicated that curcumin and demethoxycurcumin might be the core components against hepatic fibrosis, and MAPK1, EGFR, and SRC might be the core targets." (PMID 37478207, 2023).
liver fibrosis (continued). "Other studies proved that SRC is involved in proliferation and activation of HSCs, impacts cellular autophagy, and induces the platelet derived growth factor receptor (PDGFR) and transforming growth factor beta (TGF-β) signaling cascades, thus accelerating the development of liver fibrosis." (PMID 35707473, 2022).
oral cancer (11 papers, 2013 to 2021). "Similarly, SRC expression has been correlated with nodal metastasis, advanced clinical stages, recurrence, and poor prognosis in patients with oral carcinomas." (PMID 31731442, 2019). "Recent reports have demonstrated that NC inhibits tumor cell growth and cell metastasis via c-SRC/Fak, ERK, or Akt-associated pathways in several cancer cells; therefore, we cannot exclude the possibility of involvement of other kinases in NC-mediated apoptosis of oral cancer cells." (PMID 29207645, 2017).
head and neck squamous cell carcinoma (10 papers, 2009 to 2025). A squamous cell carcinoma that arises from any of the following anatomic sites: lip and oral cavity, nasal cavity, paranasal sinuses, pharynx, larynx, and salivary glands. "4-amino-5-(4-chlorophenyl)-7-(dimethyl-ethyl)pyrazolo[3,4-d] pyrimidine (PP2) is an inhibitor of the Src kinase family, being a selective inhibitor of c-SRC on head and neck squamous cell carcinoma (HNSCC), with an in vitro IC50 of 300 nM." (PMID 41155542, 2025). "Increased SRC expression and/or activity has been widely detected in a variety of human cancers, including head and neck squamous cell carcinomas (HNSCC)." (PMID 31382448, 2019). "Inhibition of SRC by SRC inhibitor Dasatinib re-sensitizes cisplatin resistant head and neck squamous cell carcinoma to cisplatin treatment." (PMID 31118072, 2019). "CTTN is a known substrate of SRC and is reported to induce gefitinib resistance in head and neck squamous cell carcinoma (HNSCC)." (PMID 29556515, 2018). "Different SRC inhibitors have demonstrated potent anti-tumor activity in preclinical models, although they largely lack clinical efficacy as monotherapy in late-stage solid tumors, including head and neck squamous cell carcinomas (HNSCC)." (PMID 31731442, 2019).
osteoporosis (10 papers, 2021 to 2026). A condition of reduced bone mass, with decreased cortical thickness and a decrease in the number and size of the trabeculae of cancellous bone (but normal chemical composition), resulting in increased fracture incidence. "The identification of EGFR, ESR1, and SRC as key regulatory hub genes provides valuable insight into the potential molecular mechanisms underlying PPIs-induced osteoporosis." (PMID 40421218, 2025). "We identified EGFR, ESR1, and SRC as key regulatory hub genes, suggesting their crucial roles in bone metabolism and the development of osteoporosis." (PMID 40421218, 2025). "This study identified EGFR, ESR1, and SRC as key regulatory genes in PPIs-induced osteoporosis, highlighting their roles in bone metabolism." (PMID 40421218, 2025). "Of these, SRC was the most highly associated and was shown to bind to PTK2B/PYK2 to provide energy for anti-osteoporosis drugs and to prevent the inhibitory effect of calcitonin by activating mitochondrial cytochrome C oxidase." (PMID 35051095, 2021). "According to topological analysis results, AKT1, MAPK1, ESR1, and SRC are critical genes for RRP to treat osteoporosis, and they have high binding activity with stigmasterol and sitosterol." (PMID 34649566, 2021). "SRC, vital in bone resorption by osteoclasts and inhibiting bone formation by osteoblasts, emerges as a potential therapeutic target in osteoporosis treatment." (PMID 39822742, 2024). "In addition to this, SRC has a role in osteoporosis in mice due to non‐functional osteoclasts." (PMID 39754479, 2025).